HDAC9 (histone deacetylase 9)
Diseases named in the same sentence as HDAC9 in open-access papers (continued):
Sharing a sentence is not in itself a finding about the gene and the disease.
cardiac hypertrophy (82 papers, 2010 to 2025). "A further novel finding, from the pathway analysis, indicated HDAC9, a gene previously linked to muscle development and cardiac hypertrophy in mouse and human." (PMID 22912587, 2012). "Loss of either HDAC5 or HDAC9 led to cardiac hypertrophy in mice." (PMID 30721967, 2019). "HDAC9 acts as a repressor of cardiac hypertrophy signalling and plays a central role in suppressing a subset of cardiac stress responses." (PMID 40497340, 2025). "The knockout of Hdac5 or Hdac9 in cardiomyocytes increased the sensitivity of mice to adverse stimuli for cardiac hypertrophy, leading to cardiac hypertrophy and cardiomyopathy." (PMID 35958418, 2022). "In contrast to class I HDACs, class II HDACs, such as HDAC5 and HDAC9, suppress cardiac hypertrophy." (PMID 35126818, 2022). "They found that MEG3 contributes to the pathogenesis of cardiac hypertrophy by competing with miR-361-5p binding and, consequently, upregulating HDAC9 expression." (PMID 34318404, 2021). "For example, loss of function of HDAC5 or HDAC9 has been associated with binding and silencing myocyte enhancer factor 2C (MEF2C), leading to a higher susceptibility to cardiac hypertrophy and cardiac failure." (PMID 33809061, 2021). "Hdac9 KO mice develop age‐dependent cardiac hypertrophy and heart failure, polydactyly, and are resistant to colitis, obesity and glucose intolerance during high‐fat feeding." (PMID 34145738, 2021). "Class IIa HDACs, containing HDAC4, HDAC5, HDAC7, and HDAC9, play protective roles during cardiac hypertrophy." (PMID 31532577, 2019). "In the heart, group IIa HDACs (HDAC4, HDAC5, HDAC7, and HDAC9) have been extensively studied and shown to be the endogenous inhibitors for cardiac hypertrophy." (PMID 30721967, 2019). "HDAC9-knockout mice are ultrasensitive to hypertrophic stimuli and spontaneously develop cardiac hypertrophy with advanced age31." (PMID 31848331, 2019). "In conclusion, this study focused on the mechanism and function of STAT3-MEG3-miR-361-5p-HDAC9 axis in cardiac hypertrophy." (PMID 30679521, 2019). "For example, overexpression of HDAC4, HDAC5, and HDAC9 suppressed myocyte enhancer factor 2 mediated gene expression to prevent pathological stimuli-induced cardiac hypertrophy." (PMID 30721967, 2019). "All our findings revealed that STAT3-inducetd upregulation of lncRNA MEG3 controls cardiac hypertrophy by regulating miR-362-5p/HDAC9 axis." (PMID 30679521, 2019). "During the development of cardiac hypertrophy, HDAC9 and other class IIa HDACs serve as anti-hypertrophic factors." (PMID 28572913, 2017). "One of the best characterized mechanisms of action of HDAC9 is its ability to interact with MEF-2 and repress MEF-2 activity, which has been linked to suppression of cardiac hypertrophy." (PMID 27642596, 2016). "Mouse knockout models for HDAC5 or HDAC9 develop profound cardiac hypertrophy in response to pressure overload and spontaneous, pathologic hypertrophy with advanced age." (PMID 24693336, 2014). "HDAC5 and HDAC9 have similar functions as endogenous inhibitors of cardiac hypertrophy in vivo." (PMID 40710369, 2025). "Among the HDACs, class IIa (HDAC4, 5, 7 and 9) are thought to be cardiac protective because overexpression of HDAC4, HDAC5, or HDAC9 in cardiac myocytes suppresses expression of a pro-hypertrophy transcription factor, Mef2 (myocyte enhancer factor-2), and reduces stress-induced cardiac hypertrophy." (PMID 36440025, 2022). "MEG3 may, therefore, function as a positive regulator in the setting of cardiac hypertrophy via its interaction with the miR-361-5p/HDAC9 axis." (PMID 34318404, 2021). "HDAC9 KO mice develop cardiac hypertrophy as they age and in response to cardiac pressure overload." (PMID 34318404, 2021). "Gene encoding the transcriptional repressor Hdac9 (Histone deacetylase 9), which acts as a negative feedback regulator of myocyte differentiation, muscle endplate reinnervation, and cardiac hypertrophy, was up-regulated (2.60-fold) in the aged muscle." (PMID 30089464, 2018).
cardiac hypertrophy (continued). "Overexpression of class IIa HDACs 4, 5, or 9 suppressed MEF2 activity, while the knockout of HDAC9 resulted in profound cardiac hypertrophy and dysfunction, it was hypothesized that HDAC inhibition would promote cardiac dysfunction and disease." (PMID 30597863, 2018). "Furthermore, MEG3 can act as a ceRNA to regulate miR-361-5p and HDAC9 in cardiac hypertrophy." (PMID 30679521, 2019). "MiR-361-5p directly targets recombinant histone deacetylase 9 (HDAC9), and thus STAT3 promotes cardiac hypertrophy." (PMID 36148063, 2022). "Current studies have only found that HDAC9 is a repressor of cardiac hypertrophy, but the specific physiological role and mechanism are not clear." (PMID 40497340, 2025). "In mouse models, the Class II HDACs HDAC9 and HDAC5 suppressed cardiac hypertrophy, and knockout mice lacking HDAC5 and HDAC9 showed spontaneous cardiac hypertrophy with age and in response to constitutive calcineurin activation or pressure overload due to aortic constriction." (PMID 39596076, 2024).
Stroke (81 papers, 2011 to 2026). Sudden impairment of blood flow to a part of the brain due to occlusion or rupture of an artery to the brain. "Large scale GWAS have identified numerous stroke‐associated SNPs, including variants linked to blood pressure regulation (e.g., HDAC9), cardioembolic stroke (e.g., MITX2), as well as variants involved in inflammatory and metabolic pathways." (PMID 41567175, 2026). "For example, HDAC9 or ANGPTL4 variants not only identify stroke susceptibility but also inform possibilities for repurposing HDAC inhibitors or enhancing ANGPTL4-mediated protection." (PMID 40863347, 2025). "HDAC9 risk alleles lead to upregulated immune cell and plaque expression and enhance stroke and other vascular diseases." (PMID 40863347, 2025). "Genome-wide association studies have identified a variant in HDAC9 related to large-vessel ischemic stroke, which is linked to enhanced stroke risk by promoting carotid atherosclerosis." (PMID 40867911, 2025). "Intriguingly, supporting the neurodetrimental role of HDAC9, polymorphisms of this gene that increase its expression levels are associated to an increased risk of stroke occurrence." (PMID 37324938, 2023). "For instance, polymorphisms in the PITX2 and ZFHX3 genes were associated with cardioembolic stroke, while markers in the 9p21 locus and the HDAC9 gene were associated with atherothrombotic stroke." (PMID 37893101, 2023). "Genome-wide association studies have revealed that genetic variants at the locus corresponding to HDAC-9 are associated with the risk of stroke, coronary artery disease and atherosclerosis due to varying levels of HDAC-9 expression." (PMID 37762023, 2023). "In our recent study, we have set up a small-scale phenotypic screening using the iPSCs-derived VSMC model with the HDAC9 stroke risk variant." (PMID 37120540, 2023). "Our group has recently developed a patient’s iPSCs-derived VSMC model for the stroke risk variant rs2107595 in the HDAC9 gene, which has the strongest association with LAS identified to date and has been linked to advanced carotid atherosclerosis." (PMID 37120540, 2023). "To address this, we developed a relevant vascular smooth muscle cells (SMC) model by using hiPSC harboring the HDAC9 stroke-associated risk variant to assess HDAC9-mediated phenotypic changes and screen the efficacy of HDAC inhibitors." (PMID 35433850, 2022). "When stratified by stroke mechanisms, HDAC9 has the strongest association with large artery stroke, and PITX2 has a close link with cardioembolic stroke." (PMID 35720094, 2022). "HDAC9 genetic variants were associated with stroke and mediate their effects through increased HDAC9 expression and increase ischemic stroke risk via promoting carotid atherosclerosis." (PMID 35087571, 2021). "The pooled odds ratios (ORs) with 95% confidence intervals (95% CIs) were calculated to assess the strengths of the associations of 3 HDAC9 gene polymorphisms with stroke risk." (PMID 28145521, 2017). "In conclusion, this meta-analysis suggested that the T allele of rs2107595 in HDAC9 increases the risk of stroke but that the G allele of rs2389995 decreases the risk of stroke in the Chinese population." (PMID 28145521, 2017). "Another GWAS on stroke in the European population revealed an association of polymorphic loci rs2107595 in HDAC9 gene susceptibility to large-vessel stroke." (PMID 27642596, 2016). "Perhaps the most exciting one so far is a gene called histone deacetylase 9 (HDAC9), which appears to be associated with large artery – or atherosclerotic – stroke." (PMID 24580858, 2014). "Now a recent GWAS published in Nature Genetics confirmed these previous associations, analyzed the specificity of the previous associations with particular stroke subtypes and identified a new association between HDAC9 and large vessel stroke." (PMID 22776031, 2012).
Stroke (continued). "The currently published GWAS of ischaemic stroke advocated the study of distinct stroke subtypes, replicated findings of previous studies and identified a new association between the A-allele of rs11984041 in HDAC9 and ischaemic stroke caused by LVD." (PMID 22776031, 2012). "Hypomethylation of HDAC9 in stroke patients also supports its upregulation as a pathogenic process." (PMID 40863347, 2025). "HDAC9 has been implicated in stroke and cardiovascular disease." (PMID 38672510, 2024). "It should be noted that HDAC9 can be induced, not only by rs2107595 polymorphism, but also by some pathophysiological conditions, such as human carotid atherosclerotic plaques 9 and stroke 10-12." (PMID 37324938, 2023). "Taken together, these findings suggest that increased HDAC9 expression observed in the stroke risk variant lines could be implicated in the altered regulation of SMC functions, including proliferation, migration, inflammation and contraction." (PMID 35433850, 2022). "The association between genetic variants of HDAC9 and stroke has been confirmed by GWASs." (PMID 35345488, 2022). "We generated vascular smooth muscle cells using human induced pluripotent stem cells with the HDAC9 stroke risk variant to assess HDAC9-mediated phenotypic changes in a relevant cells model and test the efficacy of HDAC inhibitors for potential therapeutic strategies." (PMID 35433850, 2022). "To assess the effect of HDAC9 risk variant on vascular cell phenotypes, we compared two hiPSC lines carrying the stroke risk homozygous variant rs2107595 (HDAC9v-1 and HDAC9v-2) in the 3 UTR of HDAC9 with three wild-type (WT) hiPSC lines from healthy individuals, which were used as controls." (PMID 35433850, 2022). "In summary, our meta-analysis suggested that the T allele of rs2107595 in the HDAC9 gene increases the risk of stroke in the Chinese population, whereas the minor G allele of rs2389995 may be associated with a decreased risk of stroke." (PMID 28145521, 2017). "Therefore, we performed a meta-analysis to explore the associations between HDAC9 polymorphisms and the risk of stroke in the Chinese population." (PMID 28145521, 2017). "Further studies are needed to clarify whether these environmental factors affected the polymorphism of HDAC9 and subsequent strokes." (PMID 28145521, 2017). "Therefore, the risk alleles in this region are potentially involved in stroke risk via the modulation of HDAC9 expression." (PMID 28145521, 2017). "Several recent genome-wide association studies (GWASs) have suggested that the histone deacetylase 9 (HDAC9) gene is associated with stroke, but the reliability of these findings remains controversial, particularly for the data derived from different ethnicities and geographical locations." (PMID 28145521, 2017). "Therefore, we performed a meta-analysis to estimate the association between the three SNPs (rs2107595, rs2389995 and rs2240419) of HDAC9 and the stroke risk in the Chinese Han population." (PMID 28145521, 2017). "Hence, we designed this meta-analysis to quantify the overall genetic effects of these three HDAC9 polymorphisms on the risk of stroke in the Chinese population." (PMID 28145521, 2017). "However, our HDAC9 SMC model is the first example of “functional genomic” applied to stroke associated risk variants identified by GWAS studies and opens the way to dissect the causal role of these single SNPs on molecular and cellular phenotypes in appropriate human cells." (PMID 35433850, 2022). "A rs2107595 single-nucleotide polymorphism (SNP) outside the 3′ end of HDAC9 gene has been identified as the likely causal variant, and the association between this variant and large artery stroke has been consistently replicated in other stroke patient cohorts." (PMID 35433850, 2022).
Stroke (continued). "However, because of limitations in a cohort study of this design, and possible unidentified bias, determining whether HDAC9 inhibition does reduce stroke risk requires randomized controlled trials of SVA or other HDA9 inhibitors." (PMID 29247141, 2018). "Hence, a more specific inhibitor of HDAC9 might have a stronger effect in reducing the risk of recurrent stroke." (PMID 29247141, 2018). "However, in an effort to identify genetic factors that contribute to increased risk of stroke, a large genome-wide association study has identified that a variant in HDAC9 on chromosome 7p21.1 is associated with a 1.4-fold increase in risk for large vessel disease ischemic stroke." (PMID 28264471, 2017). "In experimental stroke models, HDAC9 physically interacts with these transcription factors and enzymatically deacetylates them, altering their transcriptional activity." (PMID 40867911, 2025). "Silencing HDAC9 inhibits these processes, suggesting it is a key player in stroke-induced neuronal damage." (PMID 40863347, 2025). "HDAC9 promotes neuronal ferroptosis after stroke by increasing HIF-1 activity, which increases the iron importer TfR1, and decreases the Sp1 levels, which inhibits the protective enzyme GPX4." (PMID 40863347, 2025). "HDAC9 is expressed in a variety of cell types involved in stroke pathophysiology including glial, endothelial, smooth muscle and neuronal cells." (PMID 37324938, 2023). "Among the several isoforms of HDACs, HDAC9 has been found to play a relevant role in the neuronal death mechanisms which are activated in stroke." (PMID 37324938, 2023). "Collectively, the results of the present study suggest that stroke induced an increase in HDAC9 in the cytosol of neurons activating the pro-ferroptotic pathway HIF-1/TfR1 and reduces the anti-ferroptotic pathway Sp1/GPX4." (PMID 37324938, 2023). "Both transcriptional events contribute to the activation of the HDAC9-mediated ferroptotic cell death in stroke." (PMID 37324938, 2023). "SNPs associated with CAD, stroke, atherosclerotic aortic calcification (AAC) in the HDAC9-associated risk locus and its vicinity." (PMID 35714152, 2022). "We specifically focused on variants located within two well-characterized stroke loci: PITX2 (n = 118) and HDAC9 (n = 7)." (PMID 34992631, 2021). "For two of the six replicated loci (PITX2 and HDAC9–TWIST1), the effect size of the association (odds ratio) was bigger in the MEGASTROKE dataset than in our data (across all five summary stroke definitions)." (PMID 35185750, 2021). "To date, a stroke can be genetically associated with multiple susceptibility loci, including 9p21 (CDKN2A/CDKN2B/ANRIL), 7p21 (HDAC9), 6p21.1, 4p25 (PITX2), 16q22 (ZFHX3), 9q34 (ABO)." (PMID 33808851, 2021). "Accordingly, another paper demonstrated that the presence of HDAC9 rs2107595 and HDAC3 rs11741808 polymorphisms in combination with diabetes mellitus worsens atherosclerosis and causes stroke." (PMID 33513699, 2021). "This is emphasized by the fact that only two genes histone deacetylase 9 (HDAC9) and ALDH2, are predicted to have AS in all three causes of stroke (CE, LVD, and SVD) in either male or female patients." (PMID 33193047, 2020). "Colocalization analysis also suggested TWIST1 as a causal gene in the HDAC9/TWIST1 association locus for CAD and stroke." (PMID 31917787, 2020). "This is particularly relevant if HDAC9 inhibition is to be considered as a potential secondary preventative treatment for stroke." (PMID 29247141, 2018). "Specifically, 3 genes have been associated with atherothrombotic stroke subtype (HDAC9, CDKN (locus 9p21) and TSPAN2), 2 genes with cardioembolic stroke subtype (PITX2 and ZFHX3), and 2 genes with young strokes (ABO and MMP12)." (PMID 29321829, 2018).